EGF (epidermal growth factor)
Diseases named in the same sentence as EGF in open-access papers (continued):
Sharing a sentence is not in itself a finding about the gene and the disease.
breast carcinoma (continued). "To further characterize the signaling pathways that might contribute to both proliferation and apoptosis, we evaluated the activation of Akt, as the PI3K/Akt pathway has been described to be stimulated by both EGF and estradiol in breast cancer cells." (PMID 23239970, 2012). "EGF is an important chemoattractant, which plays a crucial role in metastasis of mammary tumors." (PMID 22790341, 2012). "Using this strategy, we found that specific ablation of EpCAM is associated with a two-fold or greater reduction in AP-1 transcription factor activity in MDA-231 breast cancer cells at baseline, or in the presence of EGF, or PMA, which are known to induce AP-1 activity." (PMID 22132731, 2011). "Therefore, our results suggest that PAK1 activation serves as a mediator of EGF-stimulated breast cancer cell migration." (PMID 23554696, 2011). "In agreement with the phenomenon observed in sarcoma cells, Pierce and colleagues showed that knocking down of MGAT5 expression, which led to decreased synthesis of galectin-3 ligands in molecules such as the EGFR, interfered with the migratory response of breast cancer cells in response to EGF." (PMID 22216245, 2011). "EGF signaling is implicated in regulating mammary gland morphogenesis and development, while aberrant EGFR activity is associated with metastasis and proliferation of breast cancer cells." (PMID 23554696, 2011). "Finally, EGF-dependent activation of p38 MAPK was effectively blocked (10 to 15 minutes) upon knock-down (gene silencing) of endogenous Brk in Brk-positive breast cancer cells." (PMID 21923922, 2011). "It is known that EGFR gene amplification indicates EGF-sensitive breast cancer." (PMID 22132735, 2011). "Furthermore, in a breast cancer cell line (MCF-7) that is routinely used as a cellular model of breast cancer, β-ARs stimulate the production of EGFRs, and EGF leads to the synthesis of the catecholamine biogenesis pathway and increased levels of epinephrine." (PMID 21476970, 2011). "Furthermore, enhanced MRP1 gene expression and a high MRP1 promoter activity have been detected in the presence of EGF in MCF-7 breast cancer cells." (PMID 22088142, 2011). "SLC37A1 is reported to be up-regulated by epidermal growth factor in breast cancer cells, leading to the suggestion that its biological role might be involved in phospholipid biosynthesis." (PMID 21949678, 2011). "EGF treatment of breast cancer cell lines upregulates hMena/hMena11a expression and phosphorylates hMena11a, suggesting cross-talk between the ErbB receptor family and hMena/hMena11a in breast cancer." (PMID 21209853, 2010). "Additional improvements in gene transfer to endothelial cells in mice with delayed-type hypersensitivity and human breast cancer cells have been achieved by coupling anti-E-selectin antibodies and folate and human epidermal growth factor (EGF) to PEGylated virus respectively." (PMID 21994645, 2010). "EGF, a growth factor regulating the proliferation and differentiation of human mammary epithelial cells, is thought to be involved in the pathophysiology of breast cancer." (PMID 20809984, 2010). "In line with this hypothesis, the recently described murine invasion isoform, Mena INV, sensitizes rat mammary tumor cells to EGF-dependent invasion and protrusion." (PMID 21209853, 2010). "The preferential upregulation of Snail1 in the ST and ST+EGF treated cells may reflect a specific set of triggers which drive EMT expression in breast cancers, in comparison to those induced with EGF alone." (PMID 19604397, 2009). "If α6β4 functions, in part, to recognize this vascular address, EGFR may help to mediate the translocation of tumor cells into the adjacent tissue, as EGF has been shown to be a potent chemotactic factor for breast carcinoma cells." (PMID 19470173, 2009). "Vav3 also potentiated EGF activity for cell growth and ERα activation in breast cancer cells." (PMID 18518979, 2008).
breast carcinoma (continued). "Common variants within the EGF gene did not appear to affect the risk of developing breast cancer, developing a tumour with high NPI, or dying from the disease." (PMID 18271972, 2008). "In addition, overexpression of EGF was correlated with tumor progression and extensive metastasis in breast cancers, and other malignancies." (PMID 18320059, 2008). "None of the tagSNPs in EGF showed association with breast cancer risk, NPI, or breast cancer survival that withstood multiple testing correction." (PMID 18271972, 2008). "Vav3 potentiates EGF activity for cell growth and ERα activation in breast cancer cells." (PMID 18518979, 2008). "Additionally, knockdown of Brk decreases epidermal growth factor-induced (or heregulin-induced) cyclin D1 expression in breast cancer cells." (PMID 17997837, 2007). "The EGF/ERBB2 signaling pathway is clinically relevant in breast cancer." (PMID 16457699, 2005). "In the present study, we generated protein-based PLC-γ1 inhibitors consisting of PLC-γ1-SH2 domains fused to the TAT leader sequence as highly specific inhibitors to block PLC-γ1 tyrosine phosphorylation, thereby inhibiting the EGF-induced migration of EGFR/c-erbB-2-positive breast cancer cells." (PMID 14710234, 2004). "Moreover, EGF increases breast cancer cell migration in synergy with IL-1β." (PMID 38438872, 2024). "Their study demonstrated that Luteolin could suppress the EGF-induced activities of EGFR signaling in human breast cancer cell lines and suggested that STAT3, MAPK/ERK1/2, and PI3K/Akt signaling pathways are the main pathways through which Luteolin exhibits its effects on EGFR signaling." (PMID 36992138, 2023). "In fact, it has been previously observed that EGF signaling activates the first step in glycolysis with hexokinase 2 (HK2) but impedes the last step with pyruvate kinase muscle isozyme M2 (PKM2) in triple breast cancer cells, and that PKM2 expression is aberrantly high in osteosarcoma tissues." (PMID 36980255, 2023). "While the exact role of P4-PR in breast cancer development and progression is still unknown, it has been shown that PR activation can contribute to the proliferation and invasion of breast cancer cells via activated EGF signaling and induction of VEGF." (PMID 37583424, 2023). "The study suggested that high oxytocin receptor levels are associated with increased EGF sensitivity and that oxytocin receptors promote EGF-stimulated RSK activation via the mTOR pathway, leading to downstream rpS6 activation and enhanced migration of breast cancer cells." (PMID 37781188, 2023). "Moreover, PKM2 was found to be acetylated by p300 in breast cancer cells upon EGF stimulation." (PMID 35931120, 2022). "Therefore, we hypothesized that G3BP1 might regulate EGF-stimulated breast cancer cell motility through PKCζ." (PMID 36330442, 2022). "The regulation of receptor internalization seems to be a role common to the Ena/VASP family members as the silencing of also Mena impaired the clathrin‐mediated endocytosis of the EGF receptor in HeLa cells, which may account for its role in EGF‐dependent breast cancer invasion and metastasis." (PMID 33512764, 2021). "Similarly, kindlin-2 interacts with EGFR and mediates EGF-induced breast cancer cell migration." (PMID 34338144, 2021). "Phosphorylation of β-catenin at Tyr654 and Tyr142 reduces its affinity for E-cadherin and α-catenin binding, respectively, which could be responsible for the dissociation of E-cadherin from actin cytoskeleton following EGF treatment in breast cancer cells MDA-MB-468." (PMID 35127732, 2021). "Interestingly, in our previous work, we found that the binding of trastuzumab induced phosphorylation of HER2 with the phosphorylation pattern of HER2 that is different from that mediated by epidermal growth factor (EGF) in human epidermal growth factor receptor 2 (HER2)-positive breast cancer." (PMID 33557368, 2021).
breast carcinoma (continued). "We coupled this with an investigation into the pattern of ILK and integrin expression changes in PMC42-ET human breast cancer cells induced by epidermal growth factor (EGF) treatment to undergo an EMT in vitro, and assessed whether these integrin changes were necessary for EMT to occur." (PMID 33276802, 2020). "Importantly, TRPM7 mediated calcium signals further modulate EMT in breast cancer cells, which TRPM7 deficiency specifically reduces EGF-induced STAT3 phosphorylation and the expression of Vimentin, suggesting that TRPM7 is required for maintaining a mesenchymal feature in breast cancer cells." (PMID 32211326, 2020). "The detection of these three phosphorylated proteins (EGFR, MSK1/2, CREB) strongly supports a functional consequences marked by EGF pathway transcriptional activity in response to toxic agents which could be an important early step in breast cancer development." (PMID 32466334, 2020). "Although alcohol significantly enhances Brf1 expression in ER+ breast cancer cells, low dose (25mM) of alcohol alone is hard to induce transformation of nontumor breast cells (MCF-10A), while the MCF-10A cells treated with EGF are able to cause colony formation in soft agar assay." (PMID 31781337, 2019). "Finally, our data suggested that PN1 was a positive-feedback regulator of EGF signaling in breast cancer cells, which could block HtrA1 and prevent EGF cleavage, and EGF could then stimulate the metastatic spread of mammary tumors through induction of PN-1." (PMID 31501409, 2019). "Moreover, inhibition of Akt phosphorylation nullifies the directional response of EGF(−)/iEF(+) breast cancer cell motility but confers additional inhibition for EGF(+)/iEF(+)—showing the potential therapeutic value of iEFs when combined with anti-cancer drugs." (PMID 31428691, 2019). "In conclusion, our results suggested that PN-1, which is up-regulated in breast cancer cells and BCSCs through EGF/PKC/MAPK/EGR1 signaling, is related to poor prognosis and could serve as a positive-feedback regulator in breast cancer cells metastasis and stemness." (PMID 31501409, 2019). "Therefore, the effects of EGF on breast cancer cells that we observed could very well have involved other ErbBs through heterodimer formation." (PMID 31532771, 2019). "Hence, the EGF/EGFR/PKC/MEK/ERK/EGR1/PN1/HtrA1 signaling axis might be a potential therapeutic target for breast cancer treatment." (PMID 31501409, 2019). "Therefore, as it is clear from here, EGF may have additional prominent role in breast cancer since its contribution in many processes." (PMID 34466490, 2019). "Given the importance of EGF in promoting breast cancer growth and metastasis, we wanted to determine whether atorvastatin pre-treatment could influence the phosphorylation of Akt and Erk in breast cancer cells." (PMID 29763460, 2018). "For instance, work in a spontaneous mammary tumor model showed that IL-4/IL-13-activated TAMs, when exposed to tumor-derived colony-stimulating factor-1 (CSF-1), produce epidermal growth factor (EGF), which in turn promotes motility and intravasation of EGF receptor (EGFR)-expressing tumor cells." (PMID 30355585, 2018). "Therefore, we further sought to determine whether FSCN1 contributed to EGF-mediated mammary carcinoma cell migration and invasion." (PMID 29142206, 2017). "In breast cancer, TAMs have been shown to promote tumor invasion and metastasis by establishing a paracrine chemotactic loop whereby breast carcinoma cells secrete colony stimulating factor-1 (CSF-1) and TAMs secrete epidermal growth factor (EGF) to induce co-migration of both cell types." (PMID 31453214, 2016). "We spatially organized a high density of SUM-159 breast cancer cells within a confined 3D tumor region composed of Matrigel® and collagen type I. A stromal matrix of collagen type I surrounded the tumor region, which allowed diffusion of EGF through the stroma into the primary tumor." (PMID 27678304, 2016).
breast carcinoma (continued). "In addition, overexpression of p110β blocks the EGF-induced migration in breast cancer cells, suggesting abundant p110β may replace p110α to interact with EGFR and results in deficiency of active p110α." (PMID 27176481, 2016). "Since the induction of MDR-1 expression by EGF has been reported in breast cancer cells, and EGFR expression is induced as a consequence of β1 integrin ligation, we hypothesized that FNIII14-mediated inactivation of β1 integrin might impact cellular drug efflux capacity." (PMID 27622612, 2016). "In addition to the mRNA reduction of classical breast cancer subtype markers, expression of ERBB receptor family members HER3 and HER4, as well as the major ligands associated with all major ERBB family signaling molecules (EGF, BTC, HRG) were reduced." (PMID 26522776, 2015). "Besides, the stimulation of MCF-7 breast cancer cells with EGF and HRG resulted in very similar early transcription profiles up to 90 min; however, subsequent cellular phenotypes differed after 3 h, which suggests that the differentiation is around 3 h (the 9th sampling time point)." (PMID 26284108, 2015). "Therefore, it may be reasonable to think that in MCF-7 breast cancer cells, EGF-induced E-cadherin internalization could be mediated by its tyrosine phosphorylation modifications." (PMID 25678857, 2015). "The six breast cancer-associated mutations in the ADAM12-L protein include the D301H mutation in the metalloproteinase domain, G479E in the disintegrin domain, T596A and R612Q in the cysteine-rich domain, G668A in the epidermal growth factor (EGF)-like domain, and L792F in the cytoplasmic tail." (PMID 24651654, 2014). "In breast cancer cells PKCδ activity can be stimulated by E2 through activation of matrix metalloproteinases (MMPs) followed by the release of membrane‐bound heparin‐binding epidermal growth factor (HB‐EGF) and trans‐activation of the epidermal grow factor receptor (EGFR)." (PMID 24872356, 2014). "In addition, paracrine signal loops between TAMS and tumor-aiding fibroblasts that secrete CXCL12 to CXCR4 over-expressing breast cancer cells increase the effectiveness of epidermal growth factor (EGF) gradients significantly increasing the occurrence of metastasis." (PMID 25385001, 2014). "Moreover radiotherapy led to development of radiation-induced adaptive response that contributes recurrence and metastases of breast cancer by upregulating Epidermal growth factor (EGF) receptor (EGFR) and vascular endothelial growth factor (VEGF) receptor (VEGFR) related proteins." (PMID 24138843, 2013). "Mena but not other Ena/VASP proteins have been implicated in EGF-dependent breast cancer invasion and metastasis, however, how Mena is linked to the EGFR is unknown." (PMID 24076656, 2013). "Thus, we speculated that EBP50 might mask the EGFR phosphorylation site to suppress EGFR downstream signaling activation, thereby hinder EGF-induced proliferation of breast cancer cells." (PMID 22476347, 2012). "In conclusion, our newly established bi-inducible breast cancer cellular model is of broad interest since it allows mechanistic understanding of how target cells behave with PR ligand and with other PR activators such as EGF under normal and pathological contexts." (PMID 23029355, 2012). "Furthermore, EGF can promote the migration of a TNBC cell line (MDA-MB-231) through the PI3K/Akt pathway, suggesting that EGF may be involved in breast cancer progression." (PMID 21966417, 2011). "Although basal activity was slightly lower than that of the WT promoter, this did not account for the loss of inducibility by NGF and EGF, suggesting that key DNA binding sites present in this region are essential for increasing promoter activity in breast cancer cells." (PMID 21241485, 2011). "In addition, EGF and heregulin-β1 activate Brk in T47D breast cancer cells." (PMID 20687930, 2010).
breast carcinoma (continued). "Also, while EGF is an important mediator of normal mammary gland development and neoplastic transformation, the value of inhibiting EGF functioning in the treatment of breast cancer remains uncertain." (PMID 15928653, 2005). "Breast cancer cell lines showed increased cell migration and invasion upon glutathionylation of ARHGEF7 at C312 in response to both oxidative stress and epidermal growth factor (EGF)." (PMID 42146387, 2026). "STAT3 can be activated in breast cancer by a number of cytokines and growth factors, including interleukin-6 (IL-6), OSM, IGF, FGF, and EGF." (PMID 40507264, 2025). "In breast cancer, CD73 facilitates local invasion through the epidermal growth factor (EGF)/EGF receptor pathway." (PMID 40114928, 2025). "STAT5 can be activated by several cytokines or growth factors in breast cancer, including prolactin (PRL), growth hormone, epidermal growth factor (EGF), and insulin-like growth factor (IGF)." (PMID 40507264, 2025). "In breast cancer (BC), METTL3 knockdown significantly increases chemosensitivity to doxorubicin via modulation of the EGF/RAD51 signaling axis." (PMID 40406121, 2025). "This entity engages with actin cross‐linking proteins, facilitating the movement and growth of cancer cells via the EGF/ERK pathway, contributing to the formation of the cytoskeleton in breast cancer cells." (PMID 39602465, 2024). "For example, macrophages secrete epidermal growth factor (EGF) and once in close proximity, can stimulate the expression of M-sec and induce homocellular TNT formation in breast cancer cells in a paracrine manner." (PMID 38489056, 2024). "The human epidermal growth factor (HER) family plays a critical role in the development and progression of breast cancer." (PMID 39513002, 2024). "Altogether, our data suggest that the brain endothelium and EGF contribute to extravasation by promoting DOCK4/RAC1- and DOCK9/CDC42-mediated elongation and intercalation of breast cancer cells." (PMID 38762624, 2024). "PBX1 is required in EGF signaling in the ER+ breast cancer cells, as silencing of PBX1 in MCF-7 cells slowed the EGF induced cell proliferation." (PMID 39358487, 2024). "For example, addition of hepatocyte growth factor (HGF) induced resistance to epidermal growth factor inhibition in lung cancer cells, while heregulin induced resistance to HER2 kinase inhibition in breast cancer cells." (PMID 39513002, 2024). "Next, to verify the relationship between Med1 and BAP1 protein expression, it was treated with EGF, E2, and TGF-β, which are known to play an important role in breast cancer growth regulation." (PMID 38708315, 2024). "NRG1 belongs to the epidermal growth factor (EGF) family, which is crucial in linking hyperglycemic memory in breast cancer cells to malignant tumor progression." (PMID 39727977, 2024). "Studies have been conducted with genes such as EGF and hMena (cytoskeleton regulatory protein) to analyze the phosphorylation and cell proliferation of HER2+ breast cancer cells." (PMID 38137912, 2023). "A previous study reported that IL-17E synergizes with EGF and confers EGFR-TKI resistance in breast cancer." (PMID 37444399, 2023). "Crucial chemoattractant molecules in breast cancer, CXCL12 and EGF, drive the activation of ERK and Akt." (PMID 36829763, 2023). "The latest study showed that METTL3 promoted HR by regulating the EGF/RAD51 axis, leading to increased doxorubicin resistance in breast cancer cells." (PMID 37264402, 2023). "Matrine inhibited breast cancer cell migration by reducing the activation of MMP9/MMP2, P65, VEGFR1 and epidermal growth factor (EGF)." (PMID 36706149, 2023).